HNRNPKP2 (heterogeneous nuclear ribonucleoprotein K pseudogene 2)
Gene: Processed pseudogene on chromosome 2 (136,199,114 to 136,200,503, reverse strand). Ensembl gene ENSG00000227347.
Diseases named in the same sentence as HNRNPKP2 in open-access papers:
HNRNPKP2 is named in the same sentence as 3 diseases in open-access papers, as found by Europe PMC text mining. Sharing a sentence is not in itself a finding about the gene and the disease. The quoted sentences say what the papers report.
gastric cancer (1 paper, 2017). A primary or metastatic malignant neoplasm involving the stomach. "Based on them, we speculate that DC-SIGNR mediated gastric cancer liver metastasis maybe causes by HNRNPKP2 to effect on hnRNP K for further studies." (PMID 28403883, 2017). "We demonstrate that DC-SIGNR facilitates gastric cancer liver metastasis mediated by HNRNPKP2 regulated by STAT5A via the CXCL12/CXCR4 biological axis." (PMID 28403883, 2017). "Next, we employed LncPath chip to investigate the mechanism of DC-SIGNR mediated gastric cancer liver metastasis by the lncRNA HNRNPKP2." (PMID 28403883, 2017). "It is better to get more middle-late stage gastric cancer solid tumours to explore the association between DC-SIGNR and HNRNPKP2." (PMID 28403883, 2017). "DC-SIGNR promoted gastric cancer liver metastasis mediated with HNRNPKP2 which expression was regulated by STAT5A." (PMID 28403883, 2017). "Furthermore to investigated the correlation between DC-SIGNR and HNRNPKP2, the two genes expression were verified by qRT-PCR in 17 paired formalin fixed and paraffin embedded gastric cancer tissues and corresponding para-carcinoma tissues, normalizing to GAPDH." (PMID 28403883, 2017). "Linear regression analysis confirmed that DC-SIGNR expression was negatively correlated with HNRNPKP2 expression in III and IV gastric cancer FFPET (R2 = 0.85, P = 0.0004)." (PMID 28403883, 2017). "Therefore, 17 paired formalin fixed and paraffin embedded gastric cancer tissues and corresponding para-carcinoma tissues can be divided into different stages to analyze if DC-SIGNR effected HNRNPKP2 in middle-late stage." (PMID 28403883, 2017). "Additionally, the negative correlation between DC-SIGNR and HNRNPKP2 had been found not only in gastric cell lines but also in gastric cancer tissues." (PMID 28403883, 2017).
tumour (1 paper, 2017). "Our results revealed that CXCR4 was responded to HNRNRKP2 and represented an important downstream effector of HNRNPKP2 that potentially mediated the effects of this lncRNA on tumour metastasis." (PMID 28403883, 2017).
HNRNPKP2 also shares sentences with these, for which no sentence is quoted: carcinoma (1 paper).